KCNN4 (potassium calcium-activated channel subfamily N member 4)
Diseases named in the same sentence as KCNN4 in open-access papers (continued):
Sharing a sentence is not in itself a finding about the gene and the disease.
tumor (continued). "The negative correlation with mast cells suggests that KCNN4 may contribute to a reduction in inflammation and antigen presentation within the tumor microenvironment." (PMID 40952239, 2025). "This lack of association may reflect the lower frequency of these mutations in the data sets analyzed, or it may indicate that KCNN4 expression is not directly modulated by pathways governed by these tumor suppressors under basal conditions." (PMID 40952239, 2025). "KCNN4 has been shown to have positive correlations with several costimulatory molecules (CD276, CD40, CD70, CD80, CD86), immune signaling receptors (IL2RA, MICB, NT5E), and multiple TNFRSF family members, suggesting its involvement in immune modulation, inflammation, and tumor‐immune interactions." (PMID 40952239, 2025). "In addition, KCNN4 demonstrates a negative correlation with CD160, KDR, and KIR2DL1, which are associated with NK and T‐cell activation, as well as tumour angiogenesis." (PMID 40952239, 2025). "In this study, we found that KCNN4 was highly expressed in LCSCs, where KCNN4 promoted the ratio of the CD133+CD44+ subpopulation, the expression of stem cells transcription factors, and the sphere formation ability in vitro, as well as increased tumor incidence and tumor growth in vivo." (PMID 35805963, 2022). "Furthermore, the enrichment of Th2 cells in amplified CNV groups corroborates the observation that KCNN4 promotes immune regulation rather than an effective antitumor response, thereby supporting its involvement in shaping an immune‐resistant tumor microenvironment." (PMID 40952239, 2025).
cancer (73 papers, 2012 to 2025). A tumor composed of atypical neoplastic, often pleomorphic cells that invade other tissues. "Considering the strong association of KCNN4 with immune signalings which enormously influences cancer progression and treatment strategy, ENCORI database was used to predict miRNAs that directly targets KCNN4 and was meant to discover potential ce-RNA network." (PMID 39282155, 2023). "We aimed at unravelling the underlying mechanism of the contrary prognosis caused by KCNN4 via analyzing the components of TME in pan-cancer types." (PMID 35720112, 2022). "Studies have revealed that KCNN4 is implicated in various physiological processes as well as promotes the malignant phenotypes of cancer cells." (PMID 35720112, 2022). "It is unlikely that a mutation in the gene for KCa3.1, KCNN4, in cancer cells is giving rise to a H33258 permeable mutant in cancer cells, as our data show that the wild-type human KCa3.1 transfected into HEK293 cells still facilitates H33258 uptake." (PMID 33199365, 2021). "Previous studies have demonstrated that high KCNN4 expression is associated with malignant features and poor prognoses in various cancers." (PMID 32857728, 2020). "The association between GSVA scores and oncogenic pathway activity provided additional support, showing that Tregs, neutrophils, and monocytes—previously linked to KCNN4 —positively correlate with active cancer pathways, while cytotoxic and effector immune cells are suppressed." (PMID 40952239, 2025). "Therefore, we tested the role of two other proteins previously implicated in cancer cell migration: the Ca2+-activated K+ channel KCa3.1 (KCNN4) and phosphoinositide 3-kinase (PI3K)." (PMID 36522586, 2023). "In humans, overexpression is considered the main mechanism of oncochannels to contribute to the malignancy of cancer, but activating mutations in the SK4‐encoding KCNN4 gene may also contribute to the expression of abnormally regulated channels." (PMID 28557306, 2017). "KCNN4 has also been reported to be detectable in cancer extracellular vesicles in breast, colon, and melanoma cancers." (PMID 38911514, 2024). "Analysis on pan-cancer samples from TCGA showed that KCNN4 overexpressed in tumors compared with normal tissues in most common cancers, including PRAD, LUAD, and SARC." (PMID 39282155, 2023). "The results showed that the expression level of KCNN4 in pan-cancer had a Pearson correlation of −0.04, 0.15, and 0.21 with cisplatin, sorafenib, and sunitinib, respectively." (PMID 39282155, 2023). "In CC, KCNN4 activation increases the sensitivity of cells to Hoechst 33258 dye, thus improving the penetration of cytotoxic substances into cancer cells." (PMID 37408210, 2023). "As a critical calcium-activated potassium channel protein, KCNN4 regulated diverse basal molecular and biological events in cells, and it had been increasingly studied in cancer field." (PMID 39282155, 2023). "Collectively, the results revealed the distinctively different KCNN4 expression patterns between cancer and normal samples in pan-cancer datasets." (PMID 35720112, 2022). "We then analyzed the correlation between KCNN4 expression level and the survival indicators of pan-cancer patients, including OS, DSS, and PFI." (PMID 35720112, 2022). "Given that ICGs are a feasible indicator associated with efficacy of immunotherapy, we further performed correlation analysis between ICGs and KCNN4 expression in pan-cancer subtypes." (PMID 35720112, 2022). "Herein, we performed a comprehensive and systematic study of KCNN4 using pan-cancer datasets, confirming that its aberrant expression and significant downregulation of methylation levels in cancer tissues compared to non-cancerous tissues." (PMID 35720112, 2022). "Results manifested that the immune scores of four pan-cancer types in the increased-risk group, including LGG, PAAD, GBM, and KIRC, were correlated with KCNN4 expression levels." (PMID 35720112, 2022).
cancer (continued). "To evaluate the expression patterns of KCNN4, we performed differential analysis of KCNN4 expression between pan-cancer and normal control tissues at transcriptomic level based on TIMER database, and at proteomic level based on the UALCAN database." (PMID 35720112, 2022). "Herein, we analyzed associations between the expression of KCNN4 and MSI levels in pan-cancer datasets." (PMID 35720112, 2022). "Results indicated that KCNN4 was altered in 168 out of 10,508 patients, accounting for 1.6% of the total participants in the pan-cancer atlas studies." (PMID 35720112, 2022). "Overall, these results demonstrated that KCNN4 was consistently enriched in cytokine, regulation of immune system, and inflammatory response related pathways, which confirms that KCNN4 acts as an essential identity for remodeling of the TME in various cancers." (PMID 35720112, 2022). "In summary, the results obtained in this study suggest that KCNN4 is a biomarker that can predict the prognosis of several cancer types." (PMID 35720112, 2022). "The ESTIMATE algorithm was then used to calculate the immune score and stromal score of the subjects in these six pan-cancer types, followed by analysis of their correlation with KCNN4." (PMID 35720112, 2022). "Potassium Calcium-Activated Channel Subfamily N Member 4 (KCNN4) has been reported as an oncogene in various cancers." (PMID 32857728, 2020). "Among the K+ channels, the intermediate-conductance Ca2+-activated K+ channels (KCa3.1, gene name KCNN4) have been widely studied in many cancers." (PMID 27183905, 2016). "KCNA5, KCNQ1, and KCNN4 are also abnormally expressed in certain cancers." (PMID 38911514, 2024). "In addition to the regulation of immune cells, studies on the function of KCNN4 in malignant tumors have been continuously reported in recent years." (PMID 35689211, 2022). "Altogether, these results suggest that KCNN4 could be a potential biomarker for predicting the prognosis of cancer." (PMID 35720112, 2022). "The results suggest that KCNN4 may have a higher accuracy in reflecting the response rate of immunotherapy for these cancer types." (PMID 35720112, 2022). "Similarly, the stromal score was positively correlated with KCNN4 expression in most pan-cancer types in both groups, with the exception of PAAD." (PMID 35720112, 2022). "Therefore, there is an urgent need to extensively characterize the landscape of KCNN4 in pan-cancer datasets, which will provide novel insights for developing effective therapies for management of cancers." (PMID 35720112, 2022). "However, it is worth noting that most studies on KCNN4 have been restricted to a single cancer type." (PMID 35720112, 2022). "We discovered that KCNN4 expression was correlated with TMB levels in 14 pan-cancer subtypes." (PMID 35720112, 2022). "The results indicated that KCNN4 was upregulated in various cancers in TCGA." (PMID 32857728, 2020). "The cancer-promoting effects of KCNN4 have been observed in various cancers." (PMID 32857728, 2020). "KCNN4-positive staining was predominantly localized in the nucleus and cytoplasm of cancer cells." (PMID 27270322, 2016). "Likewise, the significance of KCNN4 was also well investigated in many types of malignant tumor." (PMID 39282155, 2023). "In addition, aberrant KCNN4 expression was found to promote malignant phenotypes of cancer cells." (PMID 35720112, 2022). "In addition, KCNN4 may play a completely varying physiological role in various cancer types, thereby resulting in varying survival outcomes in patients." (PMID 35720112, 2022). "Interestingly, high expression of KCNN4 played a protective role in six types of pan-cancers, including SKCM (OS: p = 0.006; DSS: p = 0.024), THYM (OS: p = 0.01), BLCA (DSS: p = 0.038; PFI: p < 0.001); PRAD (PFI = 0.032), BRCA (OS: p = 0.042), and CHOL (PFI = 0.002)." (PMID 35720112, 2022).
cancer (continued). "Importantly, the expression levels of KCNN4 were significantly higher in stage III-IV patients than in stage I-II patients in THCA and KIRC cancers, suggesting that KCNN4 may reflect the clinical progression of these two tumors." (PMID 35720112, 2022). "Likewise, increased expression of KCNN4 was reported in various cancers." (PMID 31010205, 2019). "KCa3.1 (KCNN4) has been identified as a robust prognostic biomarker and predictor of immunotherapy response across multiple cancer types." (PMID 41155636, 2025). "Patients younger than or equal to 65 years old had higher KCNN4 expression levels than patients older than 65 years old in SKCM, UCEC, PRAD, and BRCA cancers." (PMID 35720112, 2022). "Recent studies have shown that MYEOV, KCNN4, and S100A16 act as oncogenes and play vital roles in cancer progression." (PMID 34789165, 2021). "In cancer cells, KCNN2 and KCNN4 activity triggers their migration." (PMID 39716493, 2024). "Besides, KCNN4 expression was correlated to TMB and MSI levels in 14 types and 12 types of pan-cancers, respectively." (PMID 35720112, 2022). "Interestingly, we discovered that KCNN4 expression was correlated with various TIC subtypes and macrophages are the most frequently occurring cell types in different cancers." (PMID 35720112, 2022). "Previously, MYEOV, KCNN4, S100A16, and FAM83A had been reported as oncogenes in various types of cancer, which could promote the proliferation and invasion of cancer cells." (PMID 34789165, 2021). "Overall, these results suggest that KCNN4 expression is correlated with TMB, MSI, and ICGs in multiple pan-cancer datasets, combined with evidence from TIDE, convincingly indicating that it could be a robust and reliable biomarker for predicting the responses of cancer cells to immunotherapy." (PMID 35720112, 2022).
infection (5 papers, 2010 to 2025). The state of being infected such as from the introduction of a foreign agent such as serum, vaccine, antigenic substance or organism. "At P15, treatment x sex analysis revealed sex-specific effects of infection on both of these inflammatory mediators (treatment x sex, IL-13; F = 5.820, p = 0.026, KCNN4; F = 7.661, p = 0.010)." (PMID 38879567, 2024). "With respect to the female response to infection-induced neuroinflammation, there was significant upregulation in the expression of CXCL9, CXCL10, BDNF, IL-13 and KCNN4 in the medulla oblongata." (PMID 38879567, 2024).
kidney disease (2 papers, 2017 to 2025). "Genetic inactivation of Kcnn4 markedly improves kidney disease in an adult Pkd1 mouse model." (PMID 41122971, 2025).
autosomal dominant disease (1 paper, 2020). Autosomal dominant form of disease. "A certain mutation of the KCNN4 gene enhances the Ca2+ sensitivity of the Gardos channel and accounts for hereditary xerocytosis, an autosomal-dominant disease." (PMID 32733893, 2020).
KCNN4 also shares sentences with these, for which no sentence is quoted: renal fibrosis (14 papers); Stroke (12); endothelial dysfunction (11); endometrial cancer (10); autoimmune disease (9); diabetes (9); ischemic stroke (9); atrial fibrillation (7); cardiovascular diseases (7); Fabry disease (7); angiosarcoma (6); head and neck squamous cell carcinoma (6); non-small cell lung carcinoma (6); breast tumor (5); idiopathic pulmonary fibrosis (5); immune diseases (5); ovarian carcinoma (5); psoriasis (5); ulcerative colitis (5); adenocarcinoma (4); Autoimmune Disorders (4); diabetic kidney disease (4); ischemia (4); rheumatoid arthritis (4); Ureteral obstruction (4); brain tumors (3); cardiac arrhythmias (3); cervical carcinoma (3); chronic asthma (3); coronary artery disease (3).
A further 111 diseases each share a sentence with KCNN4 in 3 papers or fewer.